RNU6-979P (RNA, U6 small nuclear 979, pseudogene)
Gene: Small nuclear RNA gene on chromosome 7 (28,118,113 to 28,118,219, reverse strand). Ensembl gene ENSG00000206623.
Homologues: Orthologues: chimpanzee U6 (100% identical), macaque U6 (98% identical). Paralogues in human: RNU6-45P (85% identical), RNU6-522P (85% identical), RNU6-60P (85% identical), RNU6-12P (84% identical), RNU6-13P (84% identical), RNU6-15P (84% identical), RNU6-16P (84% identical), RNU6-32P (84% identical), RNU6-354P (84% identical), RNU6-41P (84% identical), RNU6-44P (84% identical), RNU6-562P (84% identical), and 1287 more.